GPS2P1 (G protein pathway suppressor 2 pseudogene 1)
Gene: Processed pseudogene on chromosome 9 (2,875,442 to 2,876,427, reverse strand). Ensembl gene ENSG00000236496.
Diseases named in the same sentence as GPS2P1 in open-access papers:
GPS2P1 is named in the same sentence as 2 diseases in open-access papers, as found by Europe PMC text mining. Sharing a sentence is not in itself a finding about the gene and the disease. The quoted sentences say what the papers report.
tumor (1 paper, 2020). "GPS2 and GPS2P1 are uncorrelated in normal tissue but are correlated in primary tumor samples achieving a significantly higher correlation in tumor tissue (Fisher’s r to z transformation p-value < 0.0001)." (PMID 32241256, 2020).
GPS2P1 also shares sentences with these, for which no sentence is quoted: breast carcinoma (2 papers).